EGFR (epidermal growth factor receptor)
Diseases named in the same sentence as EGFR in open-access papers (continued):
Sharing a sentence is not in itself a finding about the gene and the disease.
tumor (continued). "Additionally, tetrahydroxycurcumin prevents the tumor and cell proliferation‐promoting epidermal growth factor receptor (EGFR) pathway from being activated." (PMID 41179371, 2025). "Among these targets, VEGF and EGFR play a role in tumor cell proliferation and dissemination." (PMID 41252403, 2025). "This regulatory network has actionable interfaces with key therapies; preclinical evidence links the miR-200c/LIN28B axis to acquired resistance to EGFR tyrosine kinase inhibitors (TKIs), while the circuit’s control over PD-L1 expression modulates the tumor immune microenvironment." (PMID 41300764, 2025). "The expression of CD73SC was more frequently observed in an early tumour stage (p = 0.037), PD-L1-negative tumours (p = 0.030), non-amplified EGFR tumours (p = 0.0018), and EGFR L858R-mutated tumours (p = 0.067)." (PMID 40149368, 2025). "The mechanism of action of this agent is dual: the surface CAR mediates specific recognition and binding to EGFR-positive tumor cells, while the paclitaxel released into the target cells induces apoptosis by stabilizing microtubules and disrupting cell division." (PMID 41374968, 2025). "Subsequent studies optimized this strategy for in vitro use by combining scFv-VSV-G fusion activity with poloxamer-based adjuvants, achieving the efficient transduction of difficult-to-transduce cells like CD30+ lymphoma cells, CD34+ hematopoietic stem cells, EGFR+ tumor cells, and T cells." (PMID 40573393, 2025). "Aberrant expression of FOXP3 in ovarian and other epithelial tumors has been implicated in the suppression of antitumor immune responses, thereby promoting tumor immune evasion and contributing to oncogenic pathway activation, including cross-talk with EGFR-mediated signaling cascades." (PMID 41301890, 2025). "The underlying mechanism for increased levels of sPD-1 after certain modalities of treatment (radiotherapy, anti-EGFR therapy, and anti-PD-1 immunotherapy) may be the reactivation of tumor-specific cytotoxic T-lymphocytes." (PMID 39852160, 2025). "In vivo studies confirm dioscin’sefficacy in suppressing tumor development, highlighting its potentialas a promising treatment strategy through targeting the EGFR-survivingaxis, resulting in a particular focuson EGFR as a target for the search for new anticancer steroidal saponins." (PMID 40060836, 2025). "RTKs, such as EGFR, human epidermal growth factor receptor 2 (HER2), and VEGFR, are frequently mutated or overexpressed in various kinds of cancer, leading to uncontrolled signaling and tumor growth." (PMID 40728967, 2025). "For EGFR-mutated NSCLC brain metastases, osimertinib (a third-generation EGFR-TKI) demonstrates CNS penetration and improved progression-free survival (PFS) compared to earlier TKIs, with AI models analyzing circulating tumor DNA (ctDNA) to adjust dosing." (PMID 40722321, 2025). "Additionally, EGFR amplification, TERT promoter mutations, and chromosomal markers such as +7/-10 not only assist in diagnosis but also reveal tumor heterogeneity, providing evidence for targeted therapy." (PMID 41201287, 2025). "In this design, the aptamer can be replaced with specific sequences targeting other tumor biomarkers (e.g., EGFR, HER2), while the siRNA can be customized to target the key mRNAs associated with various diseases, thereby providing a foundational framework for personalized treatment." (PMID 40422200, 2025). "Nimotuzumab is an EGFR monoclonal antibody that blocks the epidermal growth factor receptor signaling pathway, inhibits tumor angiogenesis, and enhances radiosensitivity, thereby achieving a synergistic effect where the combined outcome surpasses the individual contributions." (PMID 41244918, 2025).
tumor (continued). "In this study, we applied a multiplex TMA strategy to profile the expression landscape of EGFR, EpCAM, TF, and TROP2 in TNBC specimens and explored associations between their expression and clinicopathological features, including tumor grade, tumor stage, HER2 status, and Ki-67 expression." (PMID 40806559, 2025). "Indeed, in CAC mouse model the deletion of EGFR in myeloid cells reduced significantly the tumor size." (PMID 39966897, 2025). "EGFR and TF expression levels were significantly elevated in stage III tumors compared to stage I and II samples, suggesting a potential association with tumor progression and invasiveness." (PMID 40806559, 2025). "Similarly, epidermal growth factor receptor (EGFR) is a well-characterized driver of tumor cell proliferation and survival." (PMID 40610494, 2025). "Furthermore, treatment with an anti-CD73 antibody resulted in tumor reduction in an EGFR-mutant mouse model." (PMID 40002883, 2025). "Observed EGFR-low expressing cells showed more invasive properties and modified the tumor microenvironment to potentiate cancer cell reoccurrence, indicating that protein expression heterogeneity can play an essential role in the development of drug resistance." (PMID 39747003, 2025). "Indeed, it is known that EGFR is consistently deregulated in both LC and mesothelioma; it can therefore be used to target Targomir specifically to tumor cells." (PMID 40284466, 2025). "Single-antigen-targeted nanovaccines, such as those addressing HER2 or EGFR, may fail to target all tumor cells effectively, particularly in highly heterogeneous cancers." (PMID 40083941, 2025). "However, as single agents, they have shown limited efficacy in EGFR‐mutated NSCLC, possibly due to low tumour mutational burden (TMB), lower PD‐L1 expression and an immunosuppressive tumour microenvironment (TME) in these patients." (PMID 39715697, 2025). "Tumor shrinkage was observed after first-generation EGFR-TKI treatment, with a PFS of 9 months." (PMID 40963567, 2025). "Intriguingly, studies suggest that SMARCB1, a recognized tumor suppressor gene in various cancers, may play a significant role influencing sensitivity to EGFR-TKI-based therapy in malignant rhabdoid tumors (MRT)." (PMID 39971779, 2025). "Hence, multi-faceted functionalities regulated by EGFR signaling contribute differently to tumor progression and impact on therapy response, thereby providing valuable avenues for treatment of advanced HNSCC." (PMID 40121428, 2025). "Pre-mixing and pre-targeting with EGFR-PEG BsAbs significantly increased mRNA-LNP delivery to the tumor tissue (over 8- and 7-fold) while reducing the radiance in the liver by a third and half compared to untargeted LNPs, respectively, 8 h after luciferase mRNA-LNP administration." (PMID 40235853, 2025). "Furthermore, the combination of RET and EGFR inhibitors showed synergistic antitumor activity in vitro and hindered tumor growth in mouse models with resistant cell xenografts." (PMID 40405293, 2025). "GFP-tagged EGFR in combination with Myc-tagged USP8-WT, USP8-P681Q, and the USP8-S718P variant as well as empty vector were transiently transfected into corticotroph tumor cells followed by immunoprecipitation with anti-GFP antibody linked agarose beads." (PMID 40544420, 2025). "Immunosuppressive TME, symbolizing by impeding T cell infiltration and incomplete cytotoxicity, suppressive tumor-associated macrophage (TAM) and regulatory T cell (Treg) recruitment, as well as inhibitory cytokines production, was related to EGFR-TKI resistance in multiple studies." (PMID 40510028, 2025). "Blocking the signal transduction of EGFR and B7-H3 to inhibit tumor growth." (PMID 40519928, 2025). "Notably, AGR2, which significantly influences the EGFR signalling axis and tumour pathogenesis, exhibited the highest increase in the expression level." (PMID 40038875, 2025).
tumor (continued). "This phenomenon suggests that Dio’s regulation of EGFR signaling may exhibit tumor type or microenvironment-dependent characteristics." (PMID 40391080, 2025). "Consistent with a specific vulnerability of EGFR-addicted cancer cells to sorafenib, gene expression analysis of tumor samples from various independent clinical trials indicates that patient response to this drug is significantly correlated with a high EGFR transcriptional score." (PMID 40846697, 2025). "DARPPC tumor expression was correlated to EGFR tumor cell expression." (PMID 40969344, 2025). "MUC4’s juxtamembrane EGF-like domains are responsible for preventing EGFR ubiquitination and degradation upon ligand stimulation, which allows for persistent activation of downstream signaling pathways essential for tumor development, such as the ERK and PI3K/Akt pathways." (PMID 40655139, 2025). "Importantly, receptor tyrosine kinases (RTK) such as EGFR signaling play critical roles in modulating the cellular activities of tumor cells, including cell proliferation." (PMID 40160442, 2025). "The expression of EGFR in tumor tissues was examined, and the results of WB experiments also showed that the expression of EGFR in tumor tissues of mice administered with gefitinib alone and gefitinib/ginsenoside Rg3 spaced sequentially was significantly lower relative to the control group." (PMID 40732366, 2025). "It is plausible that high serum CEA levels may reflect tumor dependence—or “oncogene addiction”—on mutant EGFR signaling." (PMID 40856433, 2025). "Conventional chemotherapy and EGFR-targeted therapies aimed at Scissor+ tumor cells could potentially overcome resistance mechanisms and prolong RFS in WT patients." (PMID 40098972, 2025). "They concluded that EGFR TKIs concomitant with thoracic RT or chemoradiation therapy might improve local tumor control and OS, but they also stressed that the evidence held low quality." (PMID 39148905, 2024). "The HER2 and EGFR expression of tumor xenografts in NOD-SCID mice established by the s.c. inoculation of SK-OV-3 or MDA-MB-468 cells or a mixture of SK-OV-3 cells (30%) and MDA-MB-468 cells (70%) at 6 weeks post-inoculation were assessed by flow cytometry of the dissociated tumor cells." (PMID 38711454, 2024). "In addition, ART enhances anti-tumor immunity and overcomes EGFR-TKI resistance in NSCLC at least in part by suppressing TAZ/PD-L1 signaling." (PMID 39525639, 2024). "It has been recently suggested that, regardless of the type of EGFR mutation detected in the tumor cells, LUAD patients should undergo osimertinib treatment." (PMID 39001552, 2024). "Specifically, high CD151 expression was observed in 77% of patients whose tumours did not have EGFR mutations." (PMID 38982031, 2024). "Interestingly, when Cx32 was studied in terms of its non-junctional role, it was revealed that it has the potential to prevent apoptosis by promoting tumor survival via the EGFR signaling pathway." (PMID 38672615, 2024). "Tumor‐derived exosomal circRNA_102481 may promote EGFR‐TKIs resistance in NSCLC via the miRNA‐30a‐5p/ROR1 axis." (PMID 39247621, 2024). "The cobas+/Sanger− group was significantly associated with higher tumor contents, poorly differentiated patterns, tumor necrosis, and a lower internal control cycle threshold value reported by the Idylla which suggesting the presence of increased EGFR gene copy numbers." (PMID 38687753, 2024). "EGFR overexpression in UC is correlated with high invasion, recurrence, and tumor grade." (PMID 39057170, 2024). "The potential immunosuppressive role of EGFR is supported by evidence in other tumour groups." (PMID 38744099, 2024). "However, despite the initial response, many patients eventually develop acquired resistance to EGFR-TKIs, leading to tumor relapse, treatment failure, and shortened survival, which largely limit the application of EGFR-TKIs in NSCLC treatment." (PMID 38397056, 2024).
tumor (continued). "Through in vivo studies with mice carrying target A549 tumors, the anti-EGFR immunoliposomes could be more effectively accumulated in tumors, providing effective tumor imaging and treatment." (PMID 38339090, 2024). "Programmed death ligand 1 (PD-L1) on IHC revealed a tumor proportion score (TPS) of 2% and next-generation sequencing (NGS), performed on the tumor tissue, revealed two in cis mutations of the EGFR gene: S768I, with a variant allele frequency (VAF) of 43.2%; and V774M, with a VAF of 43.6%." (PMID 39062751, 2024). "Tumor-specific markers, such as EGFR, BRAF, and HER2, enable targeted treatment options." (PMID 38668035, 2024). "Given the sensitivity of fetal tumor organoids to EGFR inhibitors, we asked whether EGF is essential for organoid culture." (PMID 39567475, 2024). "For instance, 23% and 33% of non-squamous NSCLC had point mutations in KRAS and EGFR, respectively, consistently detected by all three platforms, except in case AB, which had 32% tumor content." (PMID 38398180, 2024). "Moreover, in these reports, PDGFRA and EGFR amplifications usually occurred in distinct tumor cell populations and rarely simultaneously in the same tumor cells, although a common parental origin was postulated based on mutation analysis." (PMID 38254850, 2024). "Previous studies have highlighted the influence of the mutations in exons 19 and 21 of the epidermal growth factor receptor (EGFR), particularly the sensitivity displayed by tumor cells to epidermal growth factor receptor-tyrosine kinase inhibitor (EGFR-TKI) therapy." (PMID 38980474, 2024). "Ultimately, increased EREG and AREG from any source may confer resistance by outcompeting EGFR-targeted mAbs for EGFR binding, thus re-activating EGFR and promoting tumor growth even in the presence of EGFR-targeted mAbs." (PMID 40727266, 2024). "In wild-type EGFR cells, tumor cell-intrinsic CTLA4 could upregulate PD-L1 expression through the MEK-ERK pathway downstream of EGFR." (PMID 38426097, 2024). "Erlotinib is an FDA-approved oral HER1/EGFR tyrosine kinase inhibitor that blocks tumor cell division, produces cell cycle arrest, and initiates programmed cell death in EGFR-overexpressing human tumor cells." (PMID 38459558, 2024). "Furthermore, in melanoma, β2-AR activation by (R, R')-MNF enhances eEF2 phosphorylation, leading to reduced expression of tumor regulators such as EGFR, cyclin A, and MMP-9, thereby suppressing tumor growth and progression." (PMID 39707196, 2024). "Notably, the amplification and/or the overexpression of EGFR in tumor cells, compared to normal cells, makes this receptor an optimal target for ADC." (PMID 39000238, 2024). "Since the PI3K/Akt and PLC/PKC pathways are crucial for regulating cell survival, proliferation, migration, and invasion, the anti-tumor activity of rAj-HRP may be attributed to its inhibition of EGFR and its downstream pathways." (PMID 39519855, 2024). "A genome‐wide CRISPR/Cas9 screen has identified the enzyme phosphoribosylaminoimidazole carboxylase/phosphoribosylaminoimidazole succinocarboxamide synthetase (PAICS), which is vital in de novo purine biosynthesis and tumor development, as a potential drug target for EGFR wild‐type NSCLC." (PMID 38463398, 2024). "Transfer of EGFR to macrophages by tumor-derived EVs impaired innate antiviral immunity." (PMID 39697631, 2024). "Another example is AFM24 (CD16A-NKCEs), a bispecific IgG1-scFv fusion antibody targeting CD16A on innate immune NK cells and epidermal growth factor receptor (EGFR) on tumor cells, effectively targeting tumors expressing human epidermal growth factor receptor at similar levels." (PMID 39221244, 2024). "We might expect that the levels of exposure to EGFR-TKIs might significantly differ within a tumor mass." (PMID 38732063, 2024). "No significant influence on OS could be shown for gender (p > 0.05), molecular features like ATRX and EGFR (p > 0.05) and tumor location (p > 0.05)." (PMID 39168945, 2024).
tumor (continued). "Tumor-intrinsic B7-H3 also promotes resistance to OXP via EGFR signaling." (PMID 38370387, 2024). "Overall, EGFR-targeting inhalable immunoliposomes are successfully developed and could contribute to greater anti-tumor efficacy for NSCLC treatment." (PMID 39598567, 2024). "However, GBM22 EGFR WT tumors treated with saracatinib displayed an increase in invasive phenotype, with extensive invasion beyond the tumor boundary." (PMID 38892466, 2024). "Furthermore, these reputed CTCs were more frequently detected in patients with EGFR gene amplification in the corresponding tumour tissues." (PMID 38481938, 2024). "Importantly, our data highlight the critical role of patient tumor stratification by EGFR status, as saracatinib represents a promising therapeutic strategy that we find specific to EGFRvIII+ tumors." (PMID 38892466, 2024). "Although IHC staining of EGFR revealed a high expression density in the tumor areas, a clear differentiation between healthy and tumor tissue was difficult because of a strong staining of normal epithelial cells as well as metaplastic and dysplastic lesions in the tumor environment." (PMID 39406917, 2024). "Furthermore, our investigation unveiled a significant correlation between EGFR expression and tumor malignancy (p = 0.04), further substantiating the established connection between EGFR expression levels and tumor aggressiveness." (PMID 38785565, 2024). "Mice were sacrificed 2 days post treatment and tumor EGFR expression was measured (Western blot)." (PMID 38577322, 2024). "Furthermore, through functional assays using patient tumor-derived cell lines, EGFR amplification resulted in increased activity of the EGFR pathway." (PMID 39613893, 2024). "Next, the impact of A3B on tumor evolution with EGFR TKI therapy was examined." (PMID 38049664, 2024). "Pre-op EGFR score was not statistically associated with age, gender, tumor size, location, tumor regression grade (Mandard score), cT stage, cN, or cM stage (p>0.05)." (PMID 38650801, 2024). "Epidemiological research consistently highlights correlations between EGFR mutations and specific patient profiles, including never-smokers, females, Asians, and those with advanced tumor stages." (PMID 39650554, 2024). "As indicated in both the in vivo and ex vivo images, the EGFR Affibody–IR700Dye conjugate clearly delineated the A253 tumor compared to the MCF7 tumor, suggesting that the EGFR Affibody–IR700Dye conjugate bound to the EGFR protein and imaged an EGFR-positive tumor." (PMID 38542206, 2024). "Hence, overactivation of EGFR signaling and enhanced tumor progression is commonly observed in HER2- or HER3-overexpressing cancer cells." (PMID 38745775, 2024). "Inhibition of EGFR promotes antigen presentation an immune response to tumor cells." (PMID 38398094, 2024). "Anti-CD3 monoclonal antibody activated T cells (ATC) armed with anti-CD3 x anti-EGFR bispecific antibody (EGFR BiAb) target T cells to tumor-associated antigen (TAA) on solid tumors in a non-MHC restricted manner." (PMID 38263486, 2024). "The tumor was positive for epidermal growth factor receptor (EGFR)." (PMID 39058816, 2024). "For example, one study attempted to investigate CTCs with epidermal growth factor receptor (EGFR) mutations before and after TKI treatment and found that an increase in the number of cells was associated with tumor progression, with the emergence of additional EGFR mutations in some cases." (PMID 38398206, 2024). "The use of cetuximab monotherapy to inhibit EGFR signaling leads to compensatory activation of α5β1 integrin, which may in turn promote tumor cell migration and metastasis." (PMID 38315147, 2024). "Also, we found some interesting cases, two cases that carried EGFR L858R and T790M co‐mutation in one tumor and another tumor with only EGFR 19del, and 1 case with two KRAS hotspots in the same tumor." (PMID 38348924, 2024).